UBA6 (ubiquitin like modifier activating enzyme 6)
Description:
Activates ubiquitin by first adenylating its C-terminal glycine residue with ATP, and thereafter linking this residue to the side chain of a cysteine residue in E1, yielding a ubiquitin-E1 thioester and free AMP. Specific for ubiquitin, does not activate ubiquitin-like peptides. Also activates UBD/FAT10 conjugation via adenylation of its C-terminal glycine. Differs from UBE1 in its specificity for substrate E2 charging. Does not charge cell cycle E2s, such as CDC34. Essential for embryonic development. Isoform 2 may play a key role in ubiquitin system and may influence spermatogenesis and male fertility.
Synonyms: MOP-4; E1-L2; UBE1L2; FLJ10808
Tractability: Small molecule: a structure with a bound ligand is known; a high-quality ligand is known; it belongs to a druggable protein family. PROTAC: ubiquitination databases record sites on it; its protein half-life has been measured; a small molecule that binds it is known.
Target class: Enzyme
Gene: Protein-coding gene on chromosome 4 (67,612,652 to 67,701,199, reverse strand). Ensembl gene ENSG00000033178.
Subcellular location (Human Protein Atlas): Cytosol; Nucleoplasm
Pathways (Reactome):
Disease: Dengue Virus Attachment and Entry
Immune System: Antigen processing: Ubiquitination & Proteasome degradation
Metabolism of proteins: Synthesis of active ubiquitin: roles of E1 and E2 enzymes
Gene Ontology:
Molecular function: FAT10 activating enzyme activity; protein binding; ubiquitin activating enzyme activity; ubiquitin-like modifier activating enzyme activity
Biological process: protein ubiquitination; ubiquitin-dependent protein catabolic process; DNA damage response
Cellular component: cytoplasm; cytosol; nucleoplasm; nucleus
Genetic constraint (gnomAD): Loss-of-function variants: 38 observed, 57.38 expected, observed/expected ratio (o/e) 0.66, 90% interval 0.51 to 0.87. The upper end of that interval is the gene's LOEUF score, 0.87, which puts it in group 3 of 6, group 1 being the genes least tolerant of losing a copy. Missense variants: 614 observed, 661.32 expected, observed/expected ratio (o/e) 0.93, 90% interval 0.87 to 0.99. Synonymous variants: 205 observed, 216.35 expected, observed/expected ratio (o/e) 0.95, 90% interval 0.85 to 1.06.
Homologues: Orthologues: chimpanzee UBA6 (99% identical), macaque UBA6 (98% identical), pig UBA6 (93% identical), rabbit UBA6 (93% identical), dog UBA6 (91% identical), rat Uba6 (89% identical), guinea pig UBA6 (88% identical), mouse Uba6 (87% identical), tropical clawed frog uba6 (73% identical), zebrafish uba6 (65% identical). Paralogues in human: UBA1 (41% identical), UBA7 (35% identical), UBA2 (15% identical), UBA3 (11% identical), NAE1 (11% identical), ATG7 (10% identical), SAE1 (10% identical), MOCS3 (9% identical), UBA5 (7% identical).
Diseases named in the same sentence as UBA6 in open-access papers:
UBA6 is named in the same sentence as 36 diseases in open-access papers, as found by Europe PMC text mining. Sharing a sentence is not in itself a finding about the gene and the disease. The quoted sentences say what the papers report.
breast carcinoma (4 papers, 2017 to 2025). "In fact, among 250 invasive breast cancer tissues examined, 38% of the samples showed a weaker or undetectable expression of UBA6 compared with the normal mammary tissues, further demonstrating UBA6′s association with breast cancer progression." (PMID 31067743, 2019). "To evaluate this possibility and assess clinical relevance of the cellular phenotype of UBA6 deficiency, we examined the expression of UBA6 protein in normal mammary glands and invasive mammary carcinomas by conducting analysis of tissue microarrays (TMAs)." (PMID 29152096, 2017). "Moreover, our tissue microarray analysis shows that the expression of UBA6 is low or undetectable in a substantial population of invasive breast cancer tissues, suggesting the cancer-associated roles for the non-canonical E1." (PMID 29152096, 2017). "Transplanted mouse melanoma and breast cancer cells with genetic ablation of Uba6 show higher sensitivity to ICB than wild type tumours." (PMID 36109526, 2022). "Apart from breast cancer, abnormal expressions in UBA6 and its pairing protein were found in several types of carcinoma." (PMID 31067743, 2019). "UBA6-depleted MCF-10A cells (breast epithelial cells) went through spontaneous epithelial–mesenchymal transition (EMT)—a critical step of mammary cancer development." (PMID 31067743, 2019). "In contrast, UBA6 expression was much weaker or undetectable in 38% of total invasive breast cancer tissues examined (n=250)." (PMID 29152096, 2017). "Moreover, our study warrants further investigations on the potential of UBA6 downregulation as a biomarker or therapeutic target in a substantial population of clinical breast cancers." (PMID 29152096, 2017). "Thus, our observations that a substantial fraction of human breast cancer tissues express low or undetectable levels of UBA6 protein suggest that UBA6 downregulation during carcinogenesis plays a previously undefined role in developing invasive phenotypes of breast cancer." (PMID 29152096, 2017). "Immunohistochemical analysis of human breast cancer tissues demonstrates that 38% of invasive carcinomas express low or undetectable expression of UBA6, suggesting that downregulation of this non-canonical E1 plays a role in breast cancer development." (PMID 29152096, 2017). "Taken together, these data are consistent with the hypothesis that UBA6 downregulation promotes cancer progression such as EMT and invasion in a population of human breast cancers." (PMID 29152096, 2017). "While a couple of UBA6-dependent ubiquitination substrates, i.e., CDC42, ezrin and CUGBP1, are upregulated in cells with UBA6 depletion, it remains to be determined how downregulation of UBA6 activity impact the proteome of mammary epithelial cells during breast cancer development." (PMID 29152096, 2017).
lung carcinoma (4 papers, 2013 to 2025). "It thus appears that inhibited ubiquitination through UBA6 deficiency possesses potential as a therapeutic approach for targeting endo-lysosomal trafficking in lung cancer." (PMID 38474091, 2024). "In this study, we verified the physiological roles of UBA6 in lung cancer cells through gene-silencing siRNA targeting UBA6 (siUBA6)." (PMID 38474091, 2024). "The modulatory mechanism of UBA6 in cellular migration was determined in lung cancer cells, and the cellular responses were evaluated in UBA6 depletion." (PMID 38474091, 2024). "Knockdown of UBA6 induced the increased expression of CD63 in H1975 and other lung cancer cells, including H1299 and A549." (PMID 38474091, 2024). "Our findings suggest that knock-down of UBA6 induces lysosomal TRPML1 depletion and inhibits endosomal trafficking to lysosome, and subsequently, leads to the accumulation of MVBs and enhanced exosomal secretion in lung cancer cells." (PMID 38474091, 2024). "Similarly,UBA6 and UBE2I were not regulated by miR-200b inmetastatic lung cancer cells as they were predicted to be." (PMID 23708087, 2013).
autism (2 papers, 2017). Persistent deficits in social interaction and communication and interaction as well as a markedly restricted repertoire of activity and interest as well as repetitive patterns of behavior. "It is noteworthy that IPA of the Uba6-specific targets lists synaptic long-term potentiation among uniquely associated pathways, which might be linked to the autism-like phenotype of mice with neuron-specific Uba6 disruption." (PMID 28134249, 2017). "Uba6 knockout mice are embryonic lethal and mice with brain-specific disruption of Uba6 show defects in neuronal development and an autism-like phenotype." (PMID 29152096, 2017).
hepatocellular carcinoma (2 papers, 2019 to 2022). A malignant tumor that arises from hepatocytes. "UBA6 was up-regulated in hepatocellular carcinoma (HCC) samples compared with the parent livers, while the expressions of both samples exceeded that of the normal control group." (PMID 31067743, 2019). "UBA6 activates human leukocyte antigen F-adjacent transcript 10 (FAT10), which serves as 26S proteasome-targeting signal, to be involved in epithelial-mesenchymal transition (EMT), invasion, and apoptosis in hepatocellular carcinoma." (PMID 35629968, 2022).
ovarian carcinoma (2 papers, 2022 to 2025). A malignant neoplasm originating from the surface ovarian epithelium. "Increased expression of UBA6 and UBA6-AS1 suppresses proliferation, migration and invasion of ovarian cancer cells." (PMID 36250017, 2022).
acute myeloid leukemia (1 paper, 2022). Acute myeloid leukemia (AML) is a group of neoplasms arising from precursor cells committed to the myeloid cell-line differentiation. "TAK-243 is also undergoing Phase 1 clinical trials in patients with refractory acute myeloid leukemia (AML) to block UBA1, UBA6, and NAE targeted proteins involved in tumor cell division (ClinicalTrials.gov Identifier: NCT03816319)." (PMID 36293188, 2022).
autoimmune disease (1 paper, 2021). A disorder resulting from loss of function or tissue destruction of an organ or multiple organs, arising from humoral or cellular immune responses of the individual to their own tissue constituents. "Although some E3 ligases are reported to be critical to maintain peripheral T cell tolerance and their deficiency results in severe autoimmunity, we did not observe any sign of spontaneous autoimmune disease development in UBA6 T cell deficient mice." (PMID 35011668, 2021). "Our work has identified the important role of UBA6 in T cells and demonstrated UBA6-mediated protein degradation as a mechanism for the regulation of IFN-γ production and exacerbation of autoimmune diseases." (PMID 35011668, 2021).
behavioral disorders (1 paper, 2019). "UBA6 gene was found duplicated in patients with attention-deficit hyperactivity disorder and intellectual disorder (ID) or deleted in patients with ID and behavioral disorders." (PMID 31067743, 2019).
cervical carcinoma (1 paper, 2019). A carcinoma arising from either the exocervical squamous epithelium or the endocervical glandular epithelium. "To investigate the involvement of UBA6 in autophagy, we initially used siRNAs to KD UBA6 in H4 and HeLa cervical carcinoma cells, and examined the levels of the cytosolic (LC3B-I) and membrane-bound (LC3B-II) forms of LC3B as indicators of autophagy status." (PMID 31692446, 2019).
frontotemporal dementia (1 paper, 2019). Frontotemporal dementia (FTD) comprises a group of neurodegenerative disorders, characterized by progressive changes in behavior, executive dysfunction and language impairment, as a result of degeneration of the medial prefrontal and frontoinsular cortices. "Interestingly, the expression level of UBA6-specific USE1 was up-regulated in patients with frontotemporal dementia, which suggests that the abnormal behaviors of the whole UBA6 cascade are involved in the pathogenesis of neuronal diseases." (PMID 31067743, 2019).
glioma (1 paper, 2022). A benign or malignant brain and spinal cord tumor that arises from glial cells (astrocytes, oligodendrocytes, ependymal cells). "In the order of significance, high gene expression of UBA1, UBA6, and UBA3/NAE2 were associated with significantly shorter survival times in the French glioma dataset (chi = 26.79, p = 2.3 × 10−7, chi = 21.04, p = 4.5 × 10−6, chi = 8.79, p = 3.0 × 10−3, respectively)." (PMID 36293188, 2022).
invasive breast carcinoma (1 paper, 2017). A carcinoma that infiltrates the breast parenchyma. "Our data from MCF-10A cells suggest that perturbed UBA6 function may facilitate the development of invasive breast cancer." (PMID 29152096, 2017).
invasive carcinoma (1 paper, 2017). A carcinoma that is not confined to the epithelium, and has spread to the surrounding stroma. "We found that UBA6 deficiency impairs lumen formation in MCF-10A 3-D cultures and results in formation of tumor-like cell aggregates, which are reminiscent of the development of invasive carcinomas at early stages." (PMID 29152096, 2017).
lupus (1 paper, 2021). "In human peripheral blood CD4 and CD8 T cells, basal levels of UBA6 in lupus patients presented much lower than those in healthy controls." (PMID 35011668, 2021). "Moreover, the IFN-γ production efficiency of CD4 and CD8 T cells was negatively correlated to UBA6 levels in patients with lupus." (PMID 35011668, 2021). "Patients with lupus also had increased expression of IFN-γ positive cells, and UBA6 expression was negatively correlated with IFN-γ positive cells." (PMID 35011668, 2021).
melanoma (1 paper, 2022). A malignant, usually aggressive tumor composed of atypical, neoplastic melanocytes. "We find that inosine directly inhibits UBA6 in tumour cells, and lower level of UBA6 makes the tumour more immunogenic and this is reflected in favourable outcome following ICB therapy in human melanomas." (PMID 36109526, 2022). "To directly evaluate the relationship between UBA6 expression and ICB responses, we analysed the clinical dataset in a melanoma cohort treated with anti-CTLA445 and observed that UBA6 expression was negatively predictive of the progression-free survival of ICB-treated patients." (PMID 36109526, 2022).
prostate carcinoma (1 paper, 2017). A carcinoma that arises from epithelial cells of the prostate gland. "Similar effects of Uba6 knockdown on cellular levels of ezrin and CUGBP1 were observed in human prostate epithelial RWPE-1 cells and prostate carcinoma PC3M cells." (PMID 28134249, 2017).
triple-negative breast carcinoma (1 paper, 2017). An invasive breast carcinoma which is negative for expression of estrogen receptor (ER), progesterone receptor (PR), and human epidermal growth factor receptor 2 (HER2). "The downregulation of UBA6 was more significantly manifested in ER negative, PR negative, HER2 positive or triple negative breast cancers." (PMID 29152096, 2017).
VEXAS syndrome (1 paper, 2025). An adult-onset inflammatory disease that affects only males and is caused by somatic, not germline, mutations. "To further explore the potential therapeutic relevance of UBA6 inhibition for the treatment of VEXAS syndrome, we investigated the in vivo efficacy of IP6 in a xenograft model." (PMID 40588566, 2025). "Together, these findings establish a novel human model of VEXAS syndrome, identify key roles for UBA1 and UBA6 in disease pathogenesis, and demonstrate that UBA6 inhibition represents a promising therapeutic strategy for selectively targeting UBA1 mutant clones." (PMID 40588566, 2025). "Notably, we identified UBA6 inhibition as a unique vulnerability in UBA1 mutant cells, offering a potential therapeutic strategy for VEXAS syndrome." (PMID 40588566, 2025). "In VEXAS syndrome, dysregulation of UBA1 may drive dependency on the UBA6/FAT10 axis." (PMID 40588566, 2025).
tumor (18 papers, 2017 to 2025). "Higher UBA6 expression was associated with poor OS in tumor patients: KIRC (p=0.018), LGG (p=0.040), LUAD (p=0.046), LIHC (p=0.022)." (PMID 40046044, 2025). "This study investigated the association between the expression levels of UBA1 and UBA6 in diverse tumor types and their implications for diagnosis and prognosis." (PMID 40046044, 2025). "Functionally, loss of UBA6 in tumour cells sensitised tumour cells to the cytotoxicity of T cells and abolished the effect of inosine on T-cell-mediated tumour killing." (PMID 36109526, 2022). "UBA6 was highly expressed in human tumours compared to normal tissues and low UBA6 expression was associated with improved OS of patients in several tumour types." (PMID 36109526, 2022). "Here, a systematic series of genetic loss-of-function studies showed that loss of function of UBA6 in tumour cells led to tumour inflammation, and overcame resistance to ICB immunotherapy." (PMID 36109526, 2022). "These intrinsic events within tumor cells enhance ER stress‐associated ubiquitylation and degradation by triggering ubiquitin via the E1 activase UBA6, facilitating ubiquitin transferring to E2 conjugate UBE2Z and increasing the activities of E3 ligase FBXW7 to degrade both EZH2 and MYC." (PMID 39823459, 2025). "Additionally, certain metabolites act directly on tumor cells: inosine increases tumor cell susceptibility to T cell-mediated cytotoxicity by inhibiting the ubiquitin-activating enzyme UBA6, and can enhance immunogenicity through upregulation of antigen presentation machinery." (PMID 41048488, 2025). "Third, it enhances tumor immunogenicity by binding and inhibiting UBA6 in tumor cells to elevate immunogenicity and overcome therapeutic resistance." (PMID 41181090, 2025). "Our findings indicate that the differential expression of UBA1 and UBA6 is significantly correlated with patient survival rates, tumor grade, and cancer stage." (PMID 40046044, 2025). "More importantly, we urgently need high-throughput sequencing and biological experiments focused on UBA1- and UBA6-specific tumors to address tumor heterogeneity effectively." (PMID 40046044, 2025). "Beyond its established roles in infections and inflammation, its efficacy relies on defined concentration thresholds, tumor-intrinsic factors (e.g., ubiquitin-like modifier activating enzyme 6 [UBA6] expression), and TME nutrient status." (PMID 41181090, 2025). "Inosine increases tumor antigen levels by directly suppressing the ubiquitin-activating enzyme UBA6 in tumor cells, facilitating the recognition and destruction of tumor cells by cytotoxic immune cells." (PMID 40556945, 2025). "Researches have shown that the expression of UBA1 and UBA6 was closely related to tumor occurrence and progression." (PMID 40046044, 2025). "Inosine was also found to inhibit UBA6 on tumor cells, thus increasing tumor immunogenicity and making tumor cells more prone to T cell killing." (PMID 39436103, 2024). "On the one hand, gut microbiota can enhance ICI responses by acting on UBA6 on the surface of tumor cells, thus directly enhancing the innate immunogenicity of tumor cells." (PMID 37035188, 2023). "Our recent work demonstrated that inosine sensitized tumor cells to T cell-mediated cytotoxicity by directly binding and inhibiting the ubiquitin-activating enzyme UBA6 to amplify tumor-intrinsic immunogenicity and enhance ICI efficacy." (PMID 35488243, 2022). "Despite these limitations, our study significantly expands our knowledge of metabolite inosine augments ICB efficacy by targeting tumoural UBA6 to enhance tumour immunogenicity." (PMID 36109526, 2022). "Altogether, UBA6 deletion in tumour cells primed tumour cell-intrinsic immune response and ablated the effect of inosine on gene expression of immune response signalling." (PMID 36109526, 2022). "Collectively, our results indicate that inosine sensitises tumour cells to T-cell-mediated killing by directly inhibiting UBA6 activity." (PMID 36109526, 2022).